SPATA31F1 (SPATA31 subfamily F member 1)
Synonyms: C9orf144B; FAM205A
Tractability: Antibody: UniProt predicts a signal peptide or a membrane-spanning region; the Human Protein Atlas places it where antibodies can reach.
Gene: Protein-coding gene on chromosome 9 (34,723,053 to 34,729,488, reverse strand). Ensembl gene ENSG00000205108.
Subcellular location: Membrane
Subcellular location (Human Protein Atlas): Acrosome; Plasma membrane; Mid piece; Nucleoli fibrillar center; Principal piece
Gene Ontology:
Cellular component: nucleus; membrane
Genetic constraint (gnomAD): Loss-of-function variants: 22 observed, 76.53 expected, observed/expected ratio (o/e) 0.29, 90% interval 0.2 to 0.41. The synonymous counts are far from expectation, so gnomAD's model fits this gene poorly and the ratio says little. Missense variants: 976 observed, 1,320.4 expected, observed/expected ratio (o/e) 0.74, 90% interval 0.7 to 0.78. Synonymous variants: 364 observed, 502.75 expected, observed/expected ratio (o/e) 0.72, 90% interval 0.66 to 0.79.
Homologues: Orthologues: chimpanzee FAM205A (89% identical), macaque SPATA31F1 (81% identical), rabbit SPATA31F1 (61% identical), rat Spata31f1 (47% identical), mouse Spata31f1a (45% identical), mouse Spata31f1b (45% identical), mouse Spata31f1c (45% identical), mouse Spata31f1d (45% identical), mouse Spata31f1e (36% identical). Paralogues in human: SPATA31D1 (19% identical), SPATA31A5 (18% identical), SPATA31A7 (18% identical), SPATA31A3 (18% identical), SPATA31A1 (18% identical), SPATA31A6 (18% identical), SPATA31E1 (15% identical), SPATA31C1 (13% identical), SPATA31C2 (13% identical), SPATA31D3 (12% identical), SPATA31D4 (12% identical), SPATA31F3 (9% identical).
Diseases named in the same sentence as SPATA31F1 in open-access papers:
SPATA31F1 is named in the same sentence as 1 disease in open-access papers, as found by Europe PMC text mining. Sharing a sentence is not in itself a finding about the gene and the disease.
SPATA31F1 shares sentences with these, for which no sentence is quoted: cancer (1 paper).